ERCC6L2-AS1 (ERCC6L2 antisense RNA 1)
Synonyms: C9orf130; LINC00476; NAG12; NAG11
Gene: Long non-coding RNA gene on chromosome 9 (95,759,231 to 95,876,241, reverse strand). Ensembl gene ENSG00000175611.
Diseases named in the same sentence as ERCC6L2-AS1 in open-access papers:
ERCC6L2-AS1 is named in the same sentence as 2 diseases in open-access papers, as found by Europe PMC text mining. Sharing a sentence is not in itself a finding about the gene and the disease.
ERCC6L2-AS1 shares sentences with these, for which no sentence is quoted: cancer (2 papers); tumor (2).